CASP9 (caspase 9)
Diseases named in the same sentence as CASP9 in open-access papers (continued):
Sharing a sentence is not in itself a finding about the gene and the disease.
melanoma (continued). "Biochemical assays measuring caspase 9 (CASP-9) activity showed that forced expression of miR-181a/b significantly increased CASP-9 activity both in sensitive and in resistant melanoma cells compared to controls." (PMID 33670365, 2021). "TAP-nanoemulsion triggered apoptosis of human malignant melanoma in the lung by inhibiting Bcl-2, cyclins D1 and E, NF-κB, ERK, MEK, and MMP-1 and MMP-9 and increasing cleaved caspase-9 and caspase-3, ATM, and p21." (PMID 32908627, 2020). "In order to evaluate the molecular mechanism of FEO induced apoptosis, we treated human melanoma cells (FM94) with FEO and assessed caspase 3, caspase 9 and PARP expression." (PMID 31191820, 2019). "In our results, DHODH inactivation by leflunomide also induced apoptosis in A375 melanoma cells, and both caspase-9 and caspase-3 were cleaved, which indicating that DHODH inactivation induced intrinsic mitochondrial pathway of apoptosis in melanoma." (PMID 29348830, 2017). "Mechanistically, TRI-03 not only increases intracellular reactive oxygen species (ROS) levels by inhibiting TrxR1 activity but also decreases XIAP expression, leading to the activation of the caspase-9/caspase-3/GSDME axis and irreversible GSDME-mediated pyroptosis in melanoma cells." (PMID 40486906, 2025). "Importantly, we also observed that melatonin (1 mM) remarkably promoted vemurafenib-induced activation of cleaved caspase-3, cleaved caspase-9 and inactivation of Bcl-2 as well as cleavage of PARP in melanoma cells." (PMID 30717768, 2019). "Our previous study showed that CTPG induced apoptosis in melanoma B16-F10 cells by mitochondria-dependent pathway that increased the level of cleaved caspase-9 but not caspase-8." (PMID 30314494, 2018). "Enhanced processing of the major effector caspases (caspase-3, caspase-7, caspase-8 and caspase-9) to their active forms and cleavage of PARP (a target of activated effector caspases) was observed at 48 hours following treatment of the A375 human melanoma cells with ixazomib and bortezomib." (PMID 27783987, 2016). "It has been revealed that NCTD caused accumulation of cytosolic cytochrome c and activation of caspase-9 but not Fas-FasL pathway in a variety of cancer cells, for example, human oral cancer cells, melanoma cells and leukemic cells." (PMID 24367681, 2013). "Furthermore, both pro-apoptotic protein proteins (Cleaved caspase 9, Cleaved PARP, Bax) and mRNA (Caspase 9, Bax) levels were significantly increased in a dose-dependent manner in melanoma cells, whereas anti-apoptotic protein and mRNA level of Bcl2 was decreased sharply." (PMID 36339598, 2022). "By contrast, in melanoma IRAK-M–mediated apoptosis occurred independent of caspase-9 and caspase-8." (PMID 32533049, 2020). "Enhanced processing of major effector caspases (caspase-3, caspase-7, caspase-8 and caspase-9) to their active forms and cleavage of PARP (a target of activated effector caspases) was observed at 48 hours following treatment of the BRAF V600E mutant (A375) human melanoma cell line with ixazomib." (PMID 27783987, 2016). "No sign of caspase-8 or caspase-9 activation, but the cleavage of caspase 7 were seen upon CPT treatment in suspended melanoma." (PMID 28977882, 2017).
colon carcinoma (86 papers, 2007 to 2025). "The results revealed that B. bifidum H3-R2 in combination with L. lactis KLDS4.0325 caused apoptosis in colon cancer cells by increasing caspase-3 and caspase-9 protein levels, enhancing Bax expression, and lowering Bcl-2 expression." (PMID 39410090, 2024). "Impaired functions of the caspase 9 promoter or caspase 9 gene which leads to low activity of caspase 9 has been implicated as a cause of various cancers such as colon cancer." (PMID 27473055, 2016). "Naringenin, a flavonoid found in citrus fruits, antagonizes BPA-induced colon cancer cell proliferation and activates intrinsic apoptosis pathways via caspase-9, demonstrating its efficacy even in the presence of BPA." (PMID 41440754, 2025). "Taking into account that caspase 9 is a key protein in intrinsic apoptotic pathway 36, we analyzed its activity in HT-29 colon cancer cells after treatment with Les-6547 (5 μM) and Les-6557 (10 μM) following 24 h exposure." (PMID 40136714, 2025). "In human colon cancer HT-29 cells, luteolin treatment triggered the release of cytochrome c from mitochondria into the cytoplasm, leading to increased levels of activated caspase-9 and caspase-3." (PMID 40620671, 2025). "The protein expression of Caspase 9, an initiator caspase in the intrinsic apoptotic pathway, was also elevated under the influence of isorhamnetin in both colon cancer cell lines." (PMID 40649986, 2025). "Glabridin inhibits cancer cell proliferation by downregulating PI3K, AKT, and mTOR, upregulating Bax, caspase-3, and caspase-9, and reducing Bcl-2, inducing colon cancer cell death through the intrinsic apoptosis pathway." (PMID 39723390, 2024). "Activated Akt can regulate the expression of apoptosis-suppressing genes Bcl-2, caspase-3, caspase-9 and other proteins to mediate apoptosis in colon cancer." (PMID 36971681, 2023). "Disrupts MMP function, causes leakage of cytochrome C from mitochondria, and activates caspase-3, caspase-7, and caspase-9 expression in HT-29 colon cancer cells." (PMID 35208993, 2022). "Sitosterol decreases PI3K/Akt expression in colon cancer tissues, promotes Bad activation, decreases Bcl-xl expression, and enhances cytochrome C release, leading to caspase-9 and caspase-3 activation, PARP cleavage, and apoptosis." (PMID 36313365, 2022). "One study found that inhibition of casp-9 can induce PD-L1 upregulation in colon cancer cells, demonstrating the potential efficacy of ICIs in conjunction with pyroptosis-inducing drugs." (PMID 35846123, 2022). "Colon cancer cells hijack caspase-9 signaling to suppress the radiation-induced mitochondrial DNA–cGAS–STING sensing pathway and limit the secretion of type I IFNs." (PMID 33490069, 2020). "This study demonstrated that taurine can significantly enhance the cleaved form of caspase-9, suggesting that the mitochondrial pathway of apoptosis is involved in taurine-induced apoptosis in colon cancer." (PMID 32566100, 2020). "Concomitantly, IP6 induced apoptosis of colon cancer cells, which was accompanied by upregulated expression of caspase 9 and caspase 3 at the transcriptional level as well as an increase in caspase-3 activity." (PMID 31744065, 2019). "In thyroid, ovarian, and colon cancer cells, evodiamine led to the activation of caspase-3, caspase-8, and caspase-9." (PMID 29690562, 2018).
colon carcinoma (continued). "Herein, we revealed that NSC 95397 induces the apoptosis of colon cancer cells via activation of caspase-9, 3, 7 and PARP." (PMID 29857489, 2018). "Concomitantly, InsP6 induced apoptosis of colon cancer cells which was accompanied by upregulated expression of caspase 9 and caspase 3 at transcriptional level as well increase in caspase-3 activity." (PMID 28972559, 2017). "Markedly increased protein levels of cleaved caspase-8 and caspase-9 were detected in TSLP-treated colon cancer cells, suggesting the involvement of both pathways." (PMID 26919238, 2016). "In colon cancer cell lines, doxycycline increases the level of cytosolic cytochrome-c and triggers caspase-3 and caspase-9 activity which in turns leads to the caspase-dependent apoptosis." (PMID 26998758, 2016). "Previous studies indicated that GLU was found to significantly increase the activity of caspase-9 and -3 in colon cancer cell lines; Caco-2, NHT29 and NT84 and in Chinese hamster cells, CL-V5B." (PMID 27413637, 2016). "Taken together, these results demonstrate that activation of caspase-9 and thus, the mitochondrial pathway are essential for the induction of apoptosis in colon cancer cells depleted of Naa40." (PMID 26666750, 2016). "Knockdown of Naa40 in HCT116 and HT-29 colon cancer cells affects their survival by caspase-9 activation." (PMID 26666750, 2016). "Specifically, Naa40 knockdown in colon cancer cells activates the mitochondrial caspase-9-mediated apoptotic cascade." (PMID 26666750, 2016). "We also observed that BV induced the increasing expression of DR downstream apoptotic proteins such as cleaved caspase-3, cleaved caspase-8, cleaved caspase-9 and Bax but decreased expression of Bcl-2 in colon cancer cells." (PMID 26561202, 2015). "Caspase 9 was upregulated in Hes1 inhibited colon cancer cells, whereas down-regulated in Hes1 over-expressed cells." (PMID 26452029, 2015). "Pinocembrin induced loss of mitochondrial membrane potential with subsequent release of cytochrome c and processing of caspase-9 and -3 colon cancer cell line HCT116." (PMID 24935101, 2014). "In order to confirm this pathway, caspase-9, caspase-3 and caspase-8 activation were observed in LoVo colon cancer cells." (PMID 25342273, 2014). "Additional studies also show that quercetin in leukemia and colon cancer cells activated caspase-9 via the mitochondrial pathway; likewise, in rat hepatoma cell lines, caspase-9 can be activated by luteolin." (PMID 22456615, 2012). "It has also been reported that pretreatment of HT-29 and HCT116 colon cancer cells with individual caspase-8 or caspase-9 inhibitors (Z-IETD-FMK and Z-LEHD-FMK, respectively) prior to fucoidan exposure reduced the levels of caspases, including caspase-3." (PMID 22363242, 2011). "Following 40 hours treatment with the novel antagonist peptide, colon cancer cell Caspase 3/7 activities increased 2–7 times; Caspase 8 activities increased 2–5 times and Caspase 9 increased 1.2–1.6 times." (PMID 18261206, 2008). "Additionally, galangin can activate caspase-3 and caspase-9 in human colon cancer cells and induces apoptosis by disrupting the membrane potential of mitochondria, ultimately leading to mitochondrial dysfunction." (PMID 40620671, 2025). "The analysis of gene expression considered five genes associated with apoptosis—BCL2 (B-cell CLL/lymphoma 2), BCL2L1 (BCL2 Like 1), BCL2L2 (BCL2 Like 2), CASP3 (caspase 3), and CASP9 (caspase 9), and was carried out in human colon cancer cells exposed to the IC50 dose of BVR." (PMID 38732003, 2024). "Our study sought to assess the effect of W. somnifera L. (WS) methanolic root and stem extracts on the expression of five targeted genes (cyclooxygenase-2, caspase-9, 5-Lipoxygenase, B-cell lymphoma-extra-large, and B-cell lymphoma 2) in colon cancer cell lines (Caco-2 cell lines)." (PMID 38674831, 2024).
colon carcinoma (continued). "Moreover, the Western blotting analyses indicated that 3a and 3f were able to induced apoptosis in HCT-116 and LoVo colon cancer cells via pathways triggered by caspases, and predominantly through the intrinsic pathway mediated by caspase-9." (PMID 37895863, 2023). "By promoting Bax, Caspase-9, and Caspase-3, inhibiting Bcl-2 protein expression, and regulating the Bax/Bcl-2 apoptotic signaling pathway in human colon cancer cells, ATL III inhibits cell proliferation and induces apoptosis in HCT-116 cells, producing anti-colon cancer effects." (PMID 37241729, 2023). "Compared with normal colon cancer cells, ropivacaine could up-regulate the expression of Bax, caspase-3, a-caspase-3, caspase-9, a-caspase-9, and down-regulate the expression of bcl-2." (PMID 33345684, 2021). "Aloe-emodin-induced the apoptosis of colon cancer cells may occur by activating the mitochondrial pathway, upregulating caspase-3, caspase-9, and Bax, and downregulating the expression of Bcl-2, which may provide new ideas for future drug development." (PMID 33902610, 2021). "However, so far it has not been reported for C. ragusina L. Compound 2 was shown to activate caspase-3 and caspase-9 in human colon carcinoma HCT-116 cells and decrease tumor volume and weight in immunodeficient mice that were inoculated with HCT-116 cells." (PMID 30190676, 2018). "Expression of cleaved caspase-9 protein correlates with a longer OS in patients with Hodgkin's lymphoma, although the clinical significance of low caspase-9 expression in colon carcinoma, medulloblastoma and gastric carcinoma remains unclear." (PMID 25157404, 2014). "In colon cancer cells, Urolithin A significantly enhanced the expression of cytochrome c and elevated the levels of caspase-3 and caspase-9 in a dose-responsive way, with the stimulation of caspase-3 and caspase-9 in the cytoplasmic lysate potentially triggering apoptotic processes." (PMID 39201782, 2024). "Meanwhile, the BUB3 protein could also reverse the promotion effect of miR-664b-3p on the apoptosis of the HCT116 and DLD-1 while boosting the expression of Bcl-2 and inhibiting the production of Bax, caspase-3, and caspase-9 in colon cancer cells over-expressed of miR-664b-3p." (PMID 35156516, 2022). "In consideration that Src enhanced caspase-9 activity, and dasatinib blocked 5-Fu-triggered activation of Src, we then assessed whether a combination of dasatinib and 5-Fu could influence apoptosis in colon carcinoma cells." (PMID 29844931, 2018). "When administered in combination with 5-fluorouracil, ginsenoside Rg3 can significantly increase the apoptosis rate in colon cancer (SW620 and LoVo) cells through the activation of the Apaf1/Caspase-9/Caspase-3 pathway." (PMID 40490812, 2025). "Ginsenoside compound K, a natural product, induces an apoptosis cascade in human colon cancer cells by upregulating DR5, cleaved caspase-9 and -3 and downregulating BCL2 expression." (PMID 41465451, 2025). "The KRG extract induced apoptosis, as evidenced by the formation of apoptotic cells, an increase in the number of sub-G1-phase cells, and an increase in the levels of cleaved caspase-9, caspase-3, and PARP1 in colon cancer cells." (PMID 36079818, 2022). "Cleavage of caspase-3, including cleaved caspase-3, caspase-8, including cleaved caspase-8, and caspase-9, including cleaved caspase-9, was seen in HCT-116 and HT-29 colon cancer cells." (PMID 34834153, 2021). "In neuroblastoma cell lines, human leukemia cells, and colon cancer cells, MDZ activates caspase-9, caspase-3, and poly(ADP-ribose) polymerase, indicating the induction of the mitochondrial intrinsic pathway of apoptosis." (PMID 32131534, 2020).
colon carcinoma (continued). "Overexpression of CD44 has also been shown to promote resistance to etoposide-induced apoptosis by alteration of levels of caspase 9, caspase 3, Bcl-xl, and Bak, down-regulation of pRB, and phosphorylation of AKT in colon cancer." (PMID 25823654, 2015). "Studies have shown that inhibition of caspase-8 can increase anoikis resistance in colon cancer cells; however, inhibition of caspase-9 activity does not achieve the same results." (PMID 37667281, 2023). "We established cetuximab-resistant colon cancer cell lines SW480R and Caco-2R and knocked out PUM1 and DEAD-box helicase 5 (DDX5) with the clustered regularly interspaced short palindromic repeats (CRISPR)-caspase 9 (Cas9) system." (PMID 34447749, 2021). "Therefore, we believe SPHK1, TREG, CASP9 and IL4 can be regarded as potential drug targets that are critical for the treatment of colon cancer." (PMID 31138124, 2019). "Kumazaki and colleagues explored α-mangostin’s impact on human colon cancer cell lines (DLD-1, SW480, and COLO201), demonstrating a concentration-dependent suppression of cell growth mediated primarily through apoptosis, with involvement of caspase-9 activation and PARP-1 cleavage." (PMID 39595559, 2024). "Furthermore, Plasmodium infection promoted mitochondria-mediated apoptosis in colon cancer cells, as evidenced by the increased proportion of TUNEL-positive cells, the upregulated expression of Bax, caspase-9, and cleaved caspase-3 proteins, and the downregulated expression of Bcl-2 protein." (PMID 35668501, 2022). "This is supported by the upregulation of pro-apoptotic genes and proteins such as caspase-3, caspase-9, Bax, and cytochrome C. Further studies need to be conducted to assess the bioavailability potential of DK1 in vivo to confirm its efficacy as an anti-colon carcinoma drug." (PMID 29641445, 2018). "Western blot experiments showed in the presence of sh-LINC02418, protein level of cleaved-Caspase 9 and cleaved-Caspase 3 in CRC cells was significantly increased while BCL2 expression was inhibited, indicating silence of LINC02418 could improve cell apoptosis and reduce colon cancer cells growth." (PMID 32973404, 2020).